NLRP3 (NLR family pyrin domain containing 3)
Diseases named in the same sentence as NLRP3 in open-access papers (continued):
Sharing a sentence is not in itself a finding about the gene and the disease.
Ventricular arrhythmia (8 papers, 2016 to 2025). "Simultaneously, sympathetic nervous hyperactivity contributes to an increased susceptibility to HF-related ventricular arrhythmias due to NLRP3 inflammasome activation." (PMID 39925805, 2025). "This review aims to critically examine the mechanistic role of NLRP3 inflammasome activation in the pathogenesis of atrial and ventricular arrhythmias." (PMID 40649732, 2025). "The genetic ablation of Nlrp3 or pharmacological inhibition with MCC950 consistently attenuates ventricular arrhythmias, reduces myocardial fibrosis, and preserves conduction velocity." (PMID 40649732, 2025). "It has been demonstrated that the role of SOX2-OT lncRNA in regulating NLRP3 inflammasome-mediated ventricular arrhythmias." (PMID 37761875, 2023). "In this study, RT‒PCR and Western blotting revealed that cinnamaldehyde reduced the gene and protein expression of NLRP3 in the myocardium of rats with ventricular arrhythmia, thus reducing the release of inflammatory factors and reducing inflammatory injury to the myocardium." (PMID 40146271, 2025). "In conclusion, the NLRP3 inflammasome sits at the intersection of inflammation, fibrosis, and electrophysiological remodeling, forming a unifying mechanistic link in the pathogenesis of atrial and ventricular arrhythmias." (PMID 40649732, 2025). "The levels of SOX2-OT and NLRP3 inflammasomes could be intensified after ventricular arrhythmias." (PMID 37761875, 2023). "Another important factor in ventricular arrhythmias may be NLRP3 inflammasomes." (PMID 37761875, 2023). "This study revealed that after high-dose cinnamaldehyde treatment, mitochondrial swelling in the myocardium of SD rats with ventricular arrhythmia improved ridge rupture, reduced ROS release, and inhibited TAK1 cascade activation and NLRP3 activation." (PMID 40146271, 2025). "Our study identifies the specific associations between noise and postinfarction cardiac fibrosis, neural remodeling, ventricular arrhythmia vulnerability and P2X3/P2X7-mediated NLRP3 inflammasome-related inflammation." (PMID 35575239, 2022). "Studies have shown that cinnamaldehyde has a potential therapeutic effect on ventricular arrhythmias, and TAK1, p38MAPK and NLRP3 may be targets for its key effects." (PMID 40146271, 2025). "In the absence of TLR2, NLRP3, Caspase 1 or IL-1r, DM fails to sensitize rodents to ventricular arrhythmias." (PMID 27882934, 2016). "In the control SD rats, there were no obvious ventricular arrhythmias on ECG, the cardiac tissue and mitochondria were basically normal, the serum IL-1β level was low, and the expression of myocardial IL-1β, NLRP3, ROS, p-TAK1, p-p38MAPK and p-NF-κB was weak." (PMID 40146271, 2025).
Yersinia infection (8 papers, 2020 to 2025). "The strong IL-1 response during Yersinia infection, which requires activation of the NLRP3 inflammasome, is crucial for the animal death." (PMID 39513865, 2024). "RIPK3/MLKL-induced programmed necrosis also activates NLRP3, presumably via potassium efflux, thereby providing another route to caspase-1 engagement during Yersinia infection, even when caspase-8 cannot be activated." (PMID 39058785, 2024). "Although the NLRP3 inflammasome is activated in response to Yersinia infection or IKK/TAK1 blockade, NLRP3 and the adaptor ASC do not contribute to either caspase-8 or caspase-1 activation or cytotoxicity." (PMID 39058785, 2024). "Previous studies in intestinal epithelial cells demonstrated a critical role for integrins in activating the downstream NLRP3 signalling pathway after Yersinia infection." (PMID 37345264, 2023). "It has been suggested that co-assembly of ASC, NLRP3, RIPK3, caspase-1, and caspase-8 triggers PANoptosis during Yersinia infection." (PMID 39058785, 2024). "PANoptosomes have also been identified by immunoprecipitation during Yersinia infection, where RIPK1, RIPK3, caspase-8, FADD, ASC, and NLRP3 can be co-immunoprecipitated." (PMID 35563804, 2022). "Recently, Yersinia infection was found to activate PANoptosis, with infection inducing the formation of a PANoptosome containing RIPK1, RIPK3, caspase-8, ASC, FADD, and NLRP3." (PMID 35563804, 2022). "Interestingly, although some researchers had already identified GSDMD and GSDME activation downstream of caspase-8 after Yersinia infection, in the context of mitochondrial apoptosis, NLRP3 activation induced by K+ efflux seemed to be independent of GSDMD." (PMID 33785842, 2021). "In cells lacking NLRP3, ASC or NLRC4, caspase-1 is activated and IL-1β and IL-18 are still secreted upon Yersinia infection, suggesting that other inflammasomes are involved." (PMID 39513865, 2024).
arteriosclerosis (7 papers, 2018 to 2025). A vascular disorder characterized by thickening and hardening of the walls of the arteries. "In fact, NLRP3 has a critical role in arteriosclerosis and chronic inflammation, and in addition, the NLRP3 inflammasome acts as a major mechanism in many age-related diseases." (PMID 40725015, 2025).
cerebral malaria (7 papers, 2009 to 2024). A sequestration of Plasmodium falciparum in the brain, which can cause coma and/or seizures. "The NLRP3 inflammasome, caspase-4, caspase-8, caspase-11 and caspase-12 are crucial for regulating host inflammatory responses in cerebral malaria." (PMID 39548522, 2024). "Treatment with IL-33 following PbA-induced murine cerebral malaria reduced NLRP3 inflammasome formation and IL-1β secretion in microglia and intracerebral monocytes during the acute recovery phase." (PMID 39548522, 2024). "In rodent cerebral malaria, the role of the NLRP3 inflammasome is contentious." (PMID 39548522, 2024). "Thus, in PbA-induced murine cerebral malaria, NLRP3 functions independently of the inflammasome and the IL-1 receptor." (PMID 39548522, 2024). "The role of the NLRP3 inflammasome in rodent cerebral malaria is controversial." (PMID 39548522, 2024). "One study revealed that mice lacking NLRP3 presented delayed onset of cerebral malaria, whereas those deficient in caspase-1, the adaptor protein ASC, or the IL-1 receptor presented symptoms similar to those of wild-type mice." (PMID 39548522, 2024). "Studies in mice indicate that the inflammatory response to Plasmodium infection and the host susceptibility to experimental cerebral malaria are independent of Nlrp3 inflammasome-dependent caspase-1 activation of IL-1β and IL-18." (PMID 23405174, 2013). "While Dostert and colleagues demonstrated a partial protection to experimental cerebral malaria in NLRP3−/− mice, other studies reported that this pathological process occurs independent of NLRP3, ASC, Caspase-1, IL-1R, IL-1β, and IL-18." (PMID 24453977, 2014).
chronic hepatitis C (7 papers, 2013 to 2024). "RNA sequencing analysis comparing THP1 cells and chronic hepatitis C patient liver demonstrates that viral engagement of the NLRP3 inflammasome stimulates IL-1β production to drive proinflammatory cytokine, chemokine, and immune-regulatory gene expression networks linked with HCV disease severity." (PMID 23633957, 2013). "Infection with HCV, in both cultured cells and patients, activates the NLRP3 inflammasome of macrophages and the production of IL-1β and other cytokines which may be the mechanism driving the higher incidence of CHD in patients with chronic hepatitis C." (PMID 25438910, 2014).
co-infection (7 papers, 2015 to 2026). "We found that the protein expression of NLRP3 was significantly higher in the trachea and kidneys in the three co-infection groups than in the H9N2 and IBV groups." (PMID 35211536, 2021). "In the present study, we found that the expression levels of NLRP3 and IL-β were significantly higher in the trachea and kidneys of the co-infection groups, especially in the IBV/H9N2 group, than in the single-infection IBV and H9N2 groups." (PMID 35211536, 2021). "While nitric oxide was shown to have an inhibitory effect on the NLRP3 inflammasome, we observed that high levels of nitric oxide and IL-1β coincided during co-induction with soluble uric acid and K. pneumoniae and the opposite was observed during uric acid and S. aureus co-infection." (PMID 33322651, 2020). "Overall, co-infection with IBV and H9N2 virus increased the activity of the NLRP3 inflammasome." (PMID 35211536, 2021). "The increased expression of pro-IL-1β in monocytes/macrophages or other cells by H. pylori infection, make them vulnerable to NLRP3 inflammasome activation through increased concentration of ATP, MSU, ROS or environmental factors or co-infection with other inflammasome activating bacteria." (PMID 32230726, 2020). "In addition, we also found that Asc−/− mice, caspase-1−/− mice, and Nlrp3−/− mice exhibited comparable mortality to WT controls following co-infection with P. chabaudi and C. rodentium, as did mice lacking the LPS sensors Tlr4 or caspase-11." (PMID 33440153, 2021).
conjunctivitis (7 papers, 2016 to 2024). Inflammation of the conjunctiva of the eye. "Here, the NLRP3 inflammasome is a major driver in releasing pro-inflammatory factors such as IL-6 and caspase-1, leading to follicular conjunctivitis and bulbar congestion, even as isolated signs in the ‘asymptomatic’ patient." (PMID 37764042, 2023). "The most common ocular involvements in NLRP3-AID are conjunctivitis and papilledema, which are consistent with our study findings." (PMID 37480029, 2023). "By using this approach Hu and collaborators showed that, in Muckle–Wells Syndrome, the NLRP3-D31V mutation enhances the binding of NLRP3 with ASC resulting in an over-production of IL-1β and excessive immune responses including periodic fever, arthralgia and occasional conjunctivitis." (PMID 32560261, 2020). "NLRP3-AID generally present with low-grade fever, urticarial rash and conjunctivitis." (PMID 39618694, 2024).
cutaneous leishmaniasis (7 papers, 2017 to 2025). Leishmaniasis affecting the skin. "Researchers have shown that infections with species causing cutaneous leishmaniasis result in activation of NLRP3 inflammasomes, which plays a crucial role in host protection and clearance of the parasites." (PMID 31961876, 2020). "NLRP3 is activated in lesions of studies of humans with cutaneous leishmaniasis, whereas in a study of murine macrophages." (PMID 41451223, 2025). "An interesting study done with monocytes from cutaneous leishmaniasis patients revealed NLRP3 inflammasome activation and IL-1β production after stimulation with L. braziliensis antigens." (PMID 31961876, 2020). "In the present study, we investigated the involvement of the P2Y2 receptor in the activation of NLRP3 inflammasome elements (caspase-1 and 11) and IL-1β secretion during L. amazonensis infection in peritoneal macrophages as well as in a murine model of cutaneous leishmaniasis." (PMID 33061823, 2020). "The association of reduced lesion size and increase in pro-inflammatory gene expression is interesting, particularly given that a recent study suggests that in mice, NLRP3 inflammasome activation and IL1β production could contribute to CD8 T cell mediated pathology in murine cutaneous leishmaniasis." (PMID 32109251, 2020).
deafness (7 papers, 2016 to 2025). An inherited or acquired condition characterized by the complete loss of the ability to hear from one or both ears. "Our study suggested that syndromic deafness genes such as NLRP3 should be recognized and targeted for genetic screening of nonsyndromic deafness by targeted NGS." (PMID 27965898, 2016). "Concerning deafness, this symptom could potentially be part of a genetic syndrome, as seen in NLRP3-related syndromes, which happens to be one of the most frequently encountered genes in our case group." (PMID 37895288, 2023). "The most frequent causative deafness gene was TMC1 (DFNA36) (3 cases), followed by the next tier of genes (2 cases each) (CDH23, COCH, SLC26A4, TMPRSS3, ATP1A3), and the genes that were detected only once (ACTG1, GJB2, ILDR1, MYO7A, MYO15A, NF2, NLRP3 and SERPNB6)." (PMID 32238869, 2020).
delirium (7 papers, 2016 to 2026). A disorder characterized by confusion; inattentiveness; disorientation; illusions; hallucinations; agitation; and in some instances autonomic nervous system overactivity. "In a rat model of DHCA, machine learning-based motion sequencing (MoSeq) identified delirium-like behaviors, accompanied by hippocampal neuronal necrosis and activation of NLRP3 inflammasome." (PMID 41822169, 2026). "Cardiac surgery triggered delirium-like behaviors, concomitant with heightened microglial and NLRP3 inflammasome activation and impaired mitochondrial function and synaptic plasticity." (PMID 37968531, 2024). "Fewer NLRP3-targeting molecules are currently available in the clinic to reduce the incidence of postoperative delirium." (PMID 34079457, 2021). "The result showed that, compared with that in hippocampus and BLA of scopolamine-induced delirium rats, expression of NLRP3 in such two brain regions was decreased after WAY-100635 treatment." (PMID 27760517, 2016). "The intra-hippocampus and intra-BLA injections of WAY-100635 improved the delirium-like behavior of rats by significantly reducing the expression of NLRP3 inflammasome and the release of IL1-β and IL8 into CSF." (PMID 27760517, 2016). "This protective effect may be associated with the observed sustained downregulation of the peripheral NLRP3/caspase-1/IL-1β signaling pathway, which consequently weakens the link between early postoperative inflammation and delirium." (PMID 41998765, 2026). "However, whether liraglutide can decrease the activation of microglia by augmenting mitophagy and inhibitiing NLRP3 inflammasome, and subsequently alleviate delirium-like behaviors in elderly mice undergoing cardiac surgery remains to be elucidated." (PMID 37968531, 2024).
erectile dysfunction (7 papers, 2022 to 2026). Persistent or recurrent inability to achieve or to maintain an erection during sexual activity. "Membrane depolarization activates the NLRP3 inflammasome, with downregulation of endothelial Ca2+-activated K+ channels type 2.3 (KCa 2.3) and upregulation of endothelin-1 (ET-1) linked to erectile dysfunction." (PMID 41897372, 2026). "It was found that an increase in ROS production leads to an increase in NLRP3-mediated ET-1 expression, which induces erectile dysfunction." (PMID 41090037, 2025). "The novelty of the present study is that ET‐1‐induced erectile dysfunction depends on NLRP3 activation." (PMID 36515571, 2023). "We hypothesized that activating KCa 2.2/2.3 channels reverses erectile dysfunction and ET-1-induced NLRP3 activation in hypertensive DOCA/salt mice." (PMID 41897372, 2026). "Endothelin-1–induced erectile dysfunction depends on Recombinant Staphylococcus aureus Exfoliative toxin A- and Recombinant Staphylococcus aureus Exfoliative toxin B-mediated activation of NLRP3 in mouse corpus cavernosum via Ca2+-dependent reactive oxygen species generation." (PMID 37636019, 2023). "We then hypothesized that the knockdown of NLRP3 (ASCsLV-shNLRP3) in ASCs could promote longer cell survival in a high glucose environment and alleviate the erectile dysfunction in DMED rats via paracrine secretion." (PMID 35937790, 2022). "In conclusion, ET‐1‐induced erectile dysfunction depends on ETA‐ and ETB‐mediated activation of NLRP3 in mouse CC via Ca2+‐dependent ROS generation." (PMID 36515571, 2023).
gingivitis (7 papers, 2021 to 2026). A disorder involving inflammation of the gums; may affect surrounding and supporting structures of the teeth. "Mechanistic investigations demonstrated that the anti-gingivitis effects of DKB140 were mediated through the NF-κB/MAPK/NLRP3 signaling pathway." (PMID 41742464, 2026). "This suggests that gingivitis triggers the priming stage of the NLRP3 inflammasome, probably due to the presence of periodontopathogenic bacteria." (PMID 40427389, 2025). "As far as we know, this study provides initial insight into NLRP3 inflammasome activation at the systemic level in the context of gingivitis." (PMID 40427389, 2025). "This study aimed to determine whether gingivitis modulates the NLRP3 inflammasome in peripheral blood mononuclear cells (PBMCs) from women with PCOS." (PMID 40427389, 2025). "However, whether gingivitis is capable of modulating the inflammatory response mediated by the NLRP3 inflammasome in subjects with PCOS is an aspect that requires further exploration." (PMID 40427389, 2025). "Thus, the aim of the present study was to assess whether the presence of gingivitis is a relevant factor in the activation of the NLRP3 inflammasome in leukocytes of women with PCOS." (PMID 40427389, 2025).
Headache (7 papers, 2021 to 2025). Cephalgia, or pain sensed in various parts of the head, not confined to the area of distribution of any nerve. "Elevated levels of HMGB1 and NLRP3 were implicated in the induction of the trigeminal system, with NLRP3 levels showed a moderate positive correlation with headache severity, length of hospitalization, and headache duration, while HMGB1 levels were positively correlated with headache severity." (PMID 40688353, 2025). "These have been discussed and retrospective reviewed recently by us in a case series of 32 outpatients with headache that changed or recurred after Covid-19 vaccination, which suggest an involvement of the activation of the NLRP3 inflammation." (PMID 38431578, 2024). "In glyceryl trinitrate-induced experimental headache studies, activation of NFκβ, IL1β, IL-6 and NLRP3 inflammasome are shown within perivascular macrophages in the dura mater and in microglial cells nearby trigeminal sensory neurons in the brainstem." (PMID 34384355, 2021). "Serum NLRP3 levels were correlated with headache duration and hospital stay, while headache response to paracetamol was negatively correlated with HMGB1 and positively associated with IL-10 levels." (PMID 34384355, 2021). "Neurogenic inflammation, neuropeptides and NLRP3 inflammasome also plays a complex role in various experimental models of migraine headache." (PMID 34384355, 2021). "NLRP3 was correlated with headache duration and hospital stay, while paracetamol response was negatively associated with HMGB1 levels and positively correlated with IL-10 levels." (PMID 34384355, 2021). "While some studies have reported an association between the occurrence of headache and pro-inflammatory substances such as NLRP3, HMGB1, and interleukin 6, this has not been the case with all authors." (PMID 34979899, 2022). "Increased levels of the circulating inflammatory and/or nociceptive molecules like HMGB1, NLRP3, and IL-6 may play a role in the potential induction of the trigeminal system and manifestation of headache secondary to SARS-CoV-2 infection." (PMID 34384355, 2021). "We speculate that fatigue and headache are somewhat regulated by the NLRP3 inflammatory process." (PMID 38431578, 2024).
inflammatory skin disease (7 papers, 2015 to 2025). Inflammatory skin disorders covers a broad category that includes many conditions ranging in severity, from mild itching to grave medical health complications These disorders are common in people of all ages and races. "Therefore, regulating the NLRP3 inflammasome and its associated cytokines, including IL-1β, IL-18, and IL-6, is important in preventing inflammatory skin diseases." (PMID 37175425, 2023). "Therefore, clinical studies targeting the NLRP3 inflammasome for inflammatory skin diseases are needed." (PMID 36297328, 2022). "Furthermore, the inflammasome/IL-1β pathway is involved in the pathogenesis of various inflammatory skin diseases, and we and others have previously shown that sustained NLRP-3 inflammasome activity contributes to impaired healing in diabetic wounds." (PMID 25793779, 2015). "Among these, extensive research has focused on the roles of inflammasomes formed by NLR family members (e.g., NLRP1 and NLRP3) and the AIM2-like receptor family member AIM2 in inflammatory skin diseases." (PMID 41383588, 2025).